UCP2 (uncoupling protein 2)
Diseases named in the same sentence as UCP2 in open-access papers (continued):
Sharing a sentence is not in itself a finding about the gene and the disease.
cancer (continued). "Exosomal miR-214 inhibits uncoupling protein 2 [UCP2]-dependent autophagy and restores the tamoxifen response to cancer cells." (PMID 37035739, 2023). "SMAD4 is inactivated in several types of cancers, particularly in more than 50% of PDAC leading to an increased expression of UCP2." (PMID 36672360, 2023). "Recent studies have found that high levels of UCP2 and UCP3 appear to be beneficial for cancer cells as well as influence mitochondrial structural adaptation." (PMID 33520711, 2020). "Previous study revealed that the overexpression of mitochondrial uncoupling protein 2 (UCP2) had tight positive correlation with increased proliferation, tumorigenesis, and metabolic alterations in cancer cells." (PMID 31275989, 2019). "In case of PRMT1-driven methylation, proper mitochondrial Ca2+ uptake is reestablished by increased activity of uncoupling protein 2 (UCP2), pointing to an importance of these proteins for cancer cell survival and activity." (PMID 29113301, 2017). "In this study, we considered the recent reports on the functional interaction of UCP2 and PRMT1 and investigated the importance of this relation on cancer cell's viability, proliferation and patient's survival." (PMID 29113301, 2017). "Based on our previous work, we assume that this positive impact of UCP2 and PRMT1 on cancer cell viability and proliferation is due to a more efficient mitochondrial respiration." (PMID 29113301, 2017). "In line with this assumption, cancer cells depleted from PRMT1 and UCP2 showed an increased vulnerability and exhibited a largely decreased cell viability and proliferation." (PMID 29113301, 2017). "The inhibition of UCP2 via GNP increases the generation of mitochondrial superoxide ions, particularly in cancer cells, leading to apoptosis, cell cycle arrest, autophagy, apoptosis and the prevention of chemoresistance." (PMID 26771380, 2016). "Therefore, UCP2 may provide a new target for the treatment of cancer cells under hypoxia." (PMID 22292025, 2012). "However, the exact role of UCP2 function in cancer cells under hypoxia remains unknown." (PMID 22292025, 2012). "In fact, increased expression of UCP1 in BAT and UCP2 and UCP3 in skeletal muscle have been shown in several murine models of cancer cachexia." (PMID 24281083, 2010). "Thus, UCP2 may play an integral role in the adaptive response of cancer cells to chemotherapeutics." (PMID 20967268, 2010). "Uncoupling protein-2 (UCP2) is known to suppress mitochondrial reactive oxygen species (ROS) production and is employed by drug-resistant cancer cells to mitigate oxidative stress." (PMID 20967268, 2010). "Although UCP2 expression in the stromal tissue of our samples was not quantified, we observed positive UCP2 staining in stromal areas of precancerous lesions and cancer." (PMID 41367865, 2025). "This indicates a potential interaction between cancer cells and adipocytes, potentially involving the proteins FABP4 and UCP2, which may contribute to treatment resistance." (PMID 39823981, 2025). "However, the role of endogenous UCPs in cancer is more complex and some aspects must be taken into account when analyzing this apparent contradiction; elevated expression or activity of UCPs—especially UCP2—in cancer cells may be selected during tumor development as an adaptive mechanism." (PMID 40983641, 2025). "While the role of UCP2 in cancer is not yet clear, some studies indicate that UCP2 can either promote or suppress tumor development, depending on the stage of the tumor and cell type." (PMID 40452889, 2025). "Our observations suggest that the role of UCP2 in cancer metabolism is not universal across all cancer types." (PMID 38986826, 2024).
cancer (continued). "We observed significant variability in UCP2 expression across cancer types, with no direct correlation to their metabolic activity or proliferation rates." (PMID 38986826, 2024). "The cancer cell response to glucose and glutamine deprivation did not uniformly correlate with UCP2 abundance and cell proliferation." (PMID 38986826, 2024). "Thus far, UCP-1, UCP-2, and UCP-3 have been studied in a very limited way in cancer cachexia, and only their expression has been measured and identified, but no drug or molecule has been developed." (PMID 36900198, 2023). "In clinical studies, different correlations, negative or positive depending on the type of cancer, have been described between Ucp2 mRNA expression and patient survival." (PMID 36499405, 2022). "Furthermore, UCP2 is considered as a glucose oxidation gatekeeper; it blocks pyruvate entrance to TCA cycle, leads to shift the cancer cell metabolism and preserve the Warburg effect." (PMID 33093503, 2020). "Furthermore, analysis via The Cancer Genome Atlas (TCGA) reveals upregulation of both proteins, UCP2 and PRMT1, as common feature of various cancer types." (PMID 29113301, 2017). "Garg’s research group recently demonstrated that Che-1 cooperates with miR-2909 in the regulation of mitochondrial uncoupling protein 2 (UCP2), a critical protein whose dysregulation is involved in the pathogenesis of a number of human diseases, including cancer." (PMID 27639846, 2016). "We observed UCP2/3 dependence of mitochondrial Ca2+ in two cancer-type cell lines HeLa and Ea.hy926, whereas independency of mitochondrial Ca2+ uptake from UCP2 was observed in the respective cells from non-cancer tissue." (PMID 27642082, 2016). "The mitochondrial membrane potential is increased due to a lack of UCP2 or the removal of endogenous superoxides in dispersed islet cells and in many types of cancer cells." (PMID 26771380, 2016). "Interestingly, recent findings indicate that UCP-2 might play a functional role in the process of cancer cell biology.Its involvement in chemotherapy resistance suggests this mitochondrial uncoupling protein might serve as a potential therapeutic target for cancer treatment." (PMID 26107945, 2015). "It is tempting to speculate that depletion of cytosolic ATP by UCP2-mediated uncoupling may similarly modulate PFK activity and thereby boost glucose metabolism in cancer." (PMID 21712825, 2011). "Curiously, the impact of UCP2 on cellular ATP production is not apparent in cancer cells that have a competitive growth advantage over normal differentiated cells." (PMID 21712825, 2011). "The observed over-expression of UCP2 in cancer lines, but not in controls, provides a plausible molecular mechanism by which acetoacetate spares normal cells but suppresses growth in cancer lines." (PMID 19480693, 2009). "UCPVax is a therapeutic anti-cancer vaccine consisting of the telomerase-derived helper peptides UCP2 (TERT578–592:KSVWSKLQSIGIRQH) and UCP4 (TERT1041–1055: SLCYSILKAKNAGMS), designed to stimulate vigorous TH1 CD4 T cell responses in individuals diagnosed with cancer." (PMID 40514725, 2025). "Notably, UCP2 was not only involved in EMT and NF-κB signaling pathways across multiple malignancies but also correlated with numerous immune-related pathways in a wide range of cancer types." (PMID 41403699, 2025).
cancer (continued). "This suggests that UCP2’s function may be complemented by other mitochondrial proteins, forming a complex regulatory network rather than acting as a solitary modulator of cancer cell metabolism." (PMID 38986826, 2024). "Since proliferation and nutrient deprivation could not explain the variation in UCP2 levels in our cancer cell lines, we hypothesized that UCP2 levels may be altered under hypoxic conditions typical of the tumor environment." (PMID 38986826, 2024). "However, t it has been reported that the expression of UCP3 was significantly increased, but UCP2 expression was not significantly increased in the skeletal muscle of cancer-bearing mice." (PMID 38630690, 2024). "However, evidence also suggests that overexpression of UCP2 does not affect ROS production, but decreases glycolytic activity in cancer cells." (PMID 35874806, 2022). "Furthermore, the inhibition of UCP2, either pharmacologically with Genipin or genetically with siRNAs, was sufficient to reverse the metabolic phenotype and reduce proliferation in PaCa44 and JB6 P+ cancer cell lines." (PMID 36499405, 2022). "Notably, the contribution of UCP2 to mitochondrial Ca2+ uptake is limited to conditions of enhanced PRMT1 activity and subsequent methylation of MICU1, as the case in most cancer cells." (PMID 33614647, 2021). "Thus, the high levels of UCP2 and UCP3 observed in the cancer spheroids could contribute to the regulation of ROS levels, survival, and proliferation." (PMID 33520711, 2020). "Since PFKFB2 is highly expressed in several cancers and its expression is positively correlated with carcinogenesis, we used siRNA interference to study whether inhibition of PFKFB2 reduces tumorigenicity of UCP2 overexpressed cells." (PMID 29221144, 2017). "In particular, the negative correlation of survival probability of patients with the expression of UCP2 and PRMT1 supports our hypothesis about the impact of proper mitochondrial Ca2+ uptake on the metabolic efficiency of cancer cells that affects cancer abrasiveness and patient survival." (PMID 29113301, 2017). "Moreover, the mitochondrial membrane potential is increased due to a lack of UCP2 or the removal of endogenous superoxides in dispersed islet cells and in many types of cancer cells." (PMID 26771380, 2016). "Thus, UCP2/3 are described as sensitizer of mitochondrial Ca2+ uptake under conditions of increased PRMT1 activity, a phenomenon that has probably great importance in cancer cells." (PMID 27642082, 2016). "Recent reports suggest that modulation of ROS levels is not the only mechanism by which UCP2 may affect cancer biology." (PMID 21712825, 2011). "At the protein level, UCP2 expression in cancer cells was not as high, suggesting that both transcriptional and post-transcriptional regulation may play a role in tumorigenesis." (PMID 21935467, 2011). "In conclusion, despite the different functions of UCP2, which may have opposite effects depending on the type and stage of cancer, the authors are in global agreement that the UCP2 protein does not intervene by modulating proton leakage and thus ETC uncoupling." (PMID 36499405, 2022). "Moreover, the cancer cells used do not express identical basal levels to UCP2." (PMID 36499405, 2022). "Interestingly, UCP2 appears to be highly expressed in cancer cells (such as leukemia and pancreatic cancer) and in nondifferentiated cells with low amounts of mitochondrial tissues, which rely on glycolysis rather than oxidative phosphorylation for their energy production." (PMID 30538804, 2018). "Thus, the observed overexpression of UCP2 in cancer cells, but not in normal cells, may provide a plausible molecular mechanism by which acetoacetate spares normal cells but suppresses growth in cancer cells." (PMID 24281083, 2010).
cancer (continued). "In conclusion, the energy metabolism of cancers being very different, it is therefore important to characterize precisely their specific metabolism in order to determine whether a positive or negative targeting of UCP2 will be effective against tumor development." (PMID 36499405, 2022). "Obviously, further studies are required to explore the interrelation between UCP2/3 expression and PRMT1 activity in cancer and to reveal whether or not this function of UCP2/3 is causally linked to altered UCP2/3 expression levels in various cancer cells." (PMID 27642082, 2016).
tumor (89 papers, 2004 to 2026). "Elevated UCP2 expression has been linked to increased tumor growth, chemoresistance, and promotion of the Warburg effect." (PMID 40983641, 2025). "Loss-of-function of UCP2 markedly reduced cell proliferation, colony formation, and cell invasion and migration, while inhibiting tumor organoid or spheroid formation." (PMID 39795950, 2024). "UCP1 was associated with the impaired glucose metabolism, while UCP2 with enhanced anti-tumor immunity." (PMID 35874806, 2022). "During tumor initiation, the loss of UCP2 induced a metabolic rewiring in which most of the glucose-derived pyruvate was channelled towards the biosynthesis of fatty acids/phospholipids via mitochondrial synthesis of citrate." (PMID 35008407, 2022). "A query of the CGGA RNA-seq and the TCGA GBMLGG database demonstrated that UCP2 expression increases with increased WHO tumor-grade and is associated with a much poorer prognosis across a cohort of brain tumors." (PMID 35628447, 2022). "Collectively, these findings suggest that UCP2 acts as a tumor suppressor and is tightly linked to the aggressive phenotype of EACC." (PMID 29254145, 2017). "UCP2-mediated mitochondrial uncoupling is associated with reduced ROS generation, which may enhance tumor cell survival under oxidative stress conditions." (PMID 41403699, 2025). "The study concluded that higher ROS levels may contribute to tumor progression in UCP-2-deficient mice." (PMID 36900198, 2023). "Similarly, in the present study, the association of UCP1 with the tumor immune microenvironment in BC was minimal in comparison with UCP2." (PMID 35874806, 2022). "Additionally, UCP2 levels were positively correlated with increased amounts of lipid peroxidation and associated with neoplasia." (PMID 36499405, 2022). "Additionally, it was shown that the induction of UCP-2 makes melanoma patients susceptible to cell death protein-1 blockade therapy and elicits effective anti-tumor responses." (PMID 34481515, 2021). "In line with our hypothesis, recent studies have already linked the expression of either UCP2 or PRMT1 to tumor growth, state of metastasis and chemo resistance." (PMID 29113301, 2017). "Also, the range of tumor susceptibility to acetoacetate varies widely, plausibly due to increased levels of UCP2 expression, but other factors must be considered." (PMID 19480693, 2009). "In addition, UCP2 expression is associated with tumor grade and chemoresistance." (PMID 40362341, 2025). "However, the underlying mechanism of how UCP2 functions in the tumor growth and metabolic reprogramming process in NSCLC remains largely unknown." (PMID 38217303, 2024). "Therefore, monitoring the expression of UCP2 can help clinicians understand the metabolic profile associated with each unique tumor and give insight as to whether certain metabolic therapies may be effective." (PMID 33763373, 2021). "Some studies suggest that UCP2 promotes tumor progression by promoting aerobic glycolysis (Warburg effect) and inhibiting the generation of reactive oxygen species (ROS)." (PMID 40362341, 2025). "In some models, UCP2 induction enhances antitumor immune responses within the tumor microenvironment." (PMID 40983641, 2025). "In the later stages of tumorigenesis, UCP2 expression levels are upregulated to meet the metabolic needs of the tumor tissue, such as maintaining high ATP production, providing ROS protection, promoting therapeutic resistance, and facilitating immune evasion." (PMID 39707176, 2024). "UCP2 is downregulated before the tumor is fully formed to promote ROS accumulation and genomic instability." (PMID 39707176, 2024). "UCP2-overexpressing tumor xenografts continue to grow after chemotherapy, which links UCP2 to chemoresistance." (PMID 37744277, 2023). "The presence of UCP2 in tumor cells was another early finding and provides important clues to its biochemical function." (PMID 37175829, 2023).